SIRT4 (sirtuin 4)
Diseases named in the same sentence as SIRT4 in open-access papers (continued):
Sharing a sentence is not in itself a finding about the gene and the disease.
cancer (continued). "However, there is still only limited information regarding the clinical significance and function of SIRT4 in tumorigenesis, and all agree studies suggest that it plays a role in inhibiting cancer genes." (PMID 35842463, 2022). "Given that c-Myc negatively regulates SIRT4 and SIRT4 has been reported as a cancer suppressor, we next explored whether there is any interplay between c-Myc and SIRT4 for the cancer progression." (PMID 36371321, 2022). "SIRT4 is one of the sirtuins contained within mitochondria, and its presence or absence has been found to be correlated with many metabolism-related diseases and processes, including cancer, neurodegeneration, and aging." (PMID 36078054, 2022). "SIRT4 inhibits proliferation of several types of cancer cells." (PMID 36581622, 2022). "Moreover, for SIRT-4, the rule that its overexpression or downregulation is cancer-specific is valid." (PMID 36080416, 2022). "However, mutation of MAT2A MARylation site blocks the regulatory role of SIRT4 and promotes cancer development." (PMID 36371321, 2022). "Activation of SIRT4 could induce cell apoptosis and G2/M arrest, thereby halting cancer cell cycle progression." (PMID 33931611, 2021). "Given the vital role of apoptosis induced by ROS in carcinoma, we assessed whether SIRT4 would sensitize cells to apoptosis via ROS accumulation." (PMID 34135317, 2021). "Similarly, compared with samples of normal tissue, 19,120 human-cancer tissues also showed reduced expression of SIRT4, which were analyzed from three datasets (GTEX, TARGET, TCGA)." (PMID 33585187, 2020). "SIRT4 has an important role in suppressing cancer, so SIRT4 could be used as a new biomarker for cancer diagnosis, and to develop targets for new strategies for cancer treatment." (PMID 33585187, 2020). "SIRT1 and SIRT4 significantly decreased in 7 cancer types and 9 cancer types, respectively." (PMID 32158696, 2020). "SIRT4 expression was decreased in early stage (I–II) HCC, especially during cancer progression, indicating that downregulation of SIRT4 expression may be necessary for the initiation and maintenance of tumors." (PMID 33585187, 2020). "In addition to the regulation of mitochondrial glutamine catabolism, Sirt4 also has the capability to modulate other cancer-related cellular features such as cell cycle progression, apoptosis, invasion, and metastatic potential." (PMID 32373514, 2020). "Therefore, we expected that increasing SIRT-4‒inhibiting glucose pyruvate dehydrogenase using iBET-151 would be a feasible therapeutic strategy for these cancers." (PMID 33412753, 2020). "We reviewed mainly the function of SIRT4 in various malignant neoplasms." (PMID 33585187, 2020). "Notably, it has been shown that SIRT4-knockout mice spontaneously develop several types of tumors and SIRT4 expression is significantly down-regulated in certain human cancers." (PMID 32522234, 2020). "Together, these results suggest that SIRT4 may play an important role in controlling cell apoptosis and may have the protective function against cell death even in cancer cells." (PMID 31447696, 2019). "However, in a conflicting report, SIRT4 showed oncogenic properties, which protected cancer cells against stress-induced apoptotic cell death, such as induced by DNA damage and endoplasmic reticulum stress." (PMID 31447696, 2019). "Our previous data indicated that SIRT4 expression is repressed by a transcriptional co-repressor CtBP to contribute to the maintenance of pH homeostasis of breast cancer cells, which benefits cancer cells for their growth." (PMID 29540733, 2018). "It has been proposed that mitochondrial proteins, such as SIRT3 and SIRT4, may function as critical regulators at the crossroads between metabolism, aging, and cancer." (PMID 26785117, 2016).
cancer (continued). "However, SIRT4 knockdown and CtBP knockdown together restored decreased mitochondrial membrane potential, suggesting that the glutaminolysis is essential to maintain the proper function of mitochondria in cancer cells, which is regulated by CtBP and SIRT4." (PMID 25633289, 2015). "Based on these results, it has been proposed that mitochondrial proteins, such as SIRT3 and SIRT4, may function as critical regulators at the crossroads between metabolism, aging, and aging-related human illnesses such as cancer." (PMID 25332769, 2014). "Nevertheless, our study emphasizes the importance of both the gene and metabolite doses in their roles in cancer, and identifies SIRT4 as an oncogene that might be targeted by small molecule inhibitors, antisense oligonucleotides, etc. for the treatment of HCC." (PMID 40384857, 2025). "Through these enzymatic and non-enzymatic activities, SIRT4 tightly regulates various metabolic events, and its dysregulation is associated with diverse diseases, including type 2 diabetes, non-alcoholic fatty liver disease, obesity, and cancer 13-15." (PMID 40384857, 2025). "Therefore, the development of more potent SIRT4 inhibitors as tools for functional research, and the potential use of SIRT4 activators for cancer therapy, may represent future directions in the field of small-molecule modulators targeting SIRT4." (PMID 38773972, 2024). "Therefore, it is necessary to develop specific pharmacologic activators and inhibitors of SIRT4 that can be used as tools to understand the biology of SIRT4, and which may also be employed as a novel cancer treatment." (PMID 33585187, 2020). "Thus, we wonder whether SIRT4 is responsible for the decreased glutamine consumption upon reduction of glucose consumption in cultured cancer cells." (PMID 29540733, 2018). "In particular, it appears that Sirt4 preserves NAD+ levels through nicotinamide phosphoribosyltransferase (NAMPT) activity, while loss of Sirt4 enhances glutamine metabolism, leading to genomic instability and oncogenic phenotype, thereby suggesting a protective role of this protein against cancer." (PMID 27379175, 2016). "In addition, C-terminal-binding protein (CtBP) was found to have an essential role in promoting glutaminolysis by directly repressing the expression of SIRT4, a repressor of glutaminolysis by enzymatically modifying glutamate dehydrogenase in mitochondria, in cancer cells." (PMID 25633289, 2015). "The novel WDR79–UHRF1–SIRT4 axis underscores the centrality of SIRT4 in inhibiting the aerobic glycolysis that fuels PDAC malignancy, positioning it as a pivotal antagonist of cancer metabolism." (PMID 39682281, 2024). "SIRT1 helps cancer cells survive chemotherapy, SIRT2 inhibits cell growth, and SIRT3 controls mitochondrial health, while SIRT4, SIRT5, SIRT6, and SIRT7 each influence metabolism, angiogenesis, and metastasis." (PMID 39682281, 2024). "Mitochondrial sirtuins, especially SIRT3, SIRT4, and SIRT5, emerge as key regulators of cancer metabolism." (PMID 38331199, 2024). "Collectively, these findings suggested that SIRT4-induced autophagy further inhibited tumorigenesis and progression of PDAC, highlighting the potential of SIRT4 as a therapeutic target for cancer." (PMID 36209169, 2023). "The dysregulation of c-Myc in cancer cells promoted TRIM32 expression, which ubiquitinated SIRT4 for the proteasome-dependent degradation, thereby facilitating methionine cycle by reducing the ADP-ribosylation modification of MAT2A." (PMID 36371321, 2022). "SIRT3, SIRT4, and SIRT5 were primarily mitochondrial proteins, which have emerged as critical regulators of diverse biological events, such as cancer progression." (PMID 33282964, 2020). "The expression of SIRT4 and SIRT5 were down-regulated in cancer tissues, while SIRT6 and SIRT7 were up-regulated." (PMID 32158696, 2020).
cancer (continued). "SIRT4 is a member of the Sirtuin family (SIRT1–7) that affects cellular proliferation, stress resistance, metabolism regulation, inflammation and cancer." (PMID 31744516, 2019). "Meanwhile, related studies have shown that SIRT3, SIRT4 and SIRT6 also inhibit the Warburg effect and exert anticancer effects by regulating components of the phosphatidylinositol-3 kinase pathway, which is central to cancer metabolism." (PMID 40292294, 2025). "Mitochondrial sirtuins, (Sirtuin) SIRT3, SIRT4, and SIRT5, play crucial roles in cancer metabolism." (PMID 38331199, 2024). "SIRT4 is located in mitochondria and is a potential therapeutic target for cancer and metabolic diseases, but effective and selective SIRT4 inhibitors have not been reported." (PMID 39479446, 2024). "SIRT4 has been reported to play a role in DNA damage repair, reduce glutamine metabolism via ADP-ribosylation of glutamate dehydrogenase, and help in the suppression of cancer proliferation." (PMID 34335684, 2021). "CtBP increases glutamate dehydrogenase activity and promotes glutaminolysis by repressing SIRT4 expression as a function of glucose concentration: thus, the CtBP-SIRT4-GDH may be part of the mechanism coordinating the metabolism of glucose and glutamine in cancer cells." (PMID 34680207, 2021). "The use of a transgenic mouse model for cancer xenotransplantation has confirmed that a lack of SIRT4 can accelerate the progression of cancer cell death in various cancers by regulating glutamine metabolism in the mitochondria or the mammalian target of rapamycin (mTOR) pathways." (PMID 34335684, 2021). "In 72 paired KIRC tissues and corresponding adjacent normal tissues, expressions of SIRT4 and SIRT5 were down-regulated in cancer tissues than in normal tissues, while expressions of SIRT6 and SIRT7 were up-regulated in cancer tissues." (PMID 32158696, 2020).
metabolic disease (13 papers, 2018 to 2024). A congenital disorder (due to inherited enzyme abnormality) or acquired (due to failure of a metabolically important organ) disorder resulting from an abnormal metabolic process. "These functional characteristics of SIRT4 demonstrate its significant impact on cellular metabolism and its potential as a therapeutic target in treating metabolic diseases and conditions associated with mitochondrial dysfunction." (PMID 38773972, 2024). "The enzymology-associated SIRT4 metabolism is helpful for the development of therapeutic agents for metabolic disorders." (PMID 32365537, 2020). "SIRT4's ability to regulate insulin secretion highlights its role in maintaining glucose homeostasis, which is crucial for preventing metabolic disorders." (PMID 38773972, 2024). "More importantly, the metabolomic analysis identified glutamine metabolism disorder in mammary gland cells from SIRT4-/- mice, which is consistent with the metabolic regulatory role of SIRT4 in glutamine uptake and utilization." (PMID 32863939, 2020). "Further research is thus required to elucidate the roles of SIRT4 in relation to the benefits of exercise in prevention and treatment of metabolic diseases." (PMID 31447696, 2019). "The main goal of this review is to critically analyse and summarise the current research evidence on the significance of the SIRT4 as a metabolic regulator and in mitochondrial function and its putative roles in relation to metabolic diseases and exercise." (PMID 31447696, 2019). "A comprehensive understanding of the enzymology of SIRT4 in metabolism is essential for developing novel therapeutic agents for human metabolic diseases." (PMID 30666234, 2018). "However, the effects on SIRT4 by metabolic diseases and changes in metabolic homeostasis such as during exercise, along with the roles of SIRT4 in the regulation of metabolism during disease, are not well understood." (PMID 31447696, 2019). "Based on the background information above, this review is focused on a critical analysis of the known and potential roles of SIRT4 in regulation of cellular metabolic and energetic state, mitochondrial energy transfer, mitochondrial survival, redox regulation and metabolic diseases." (PMID 31447696, 2019). "Therefore, further research is needed to identify the possible beneficial roles of SIRT4 modulation in relation to metabolic diseases." (PMID 31447696, 2019). "Due to the important role of SIRT4 and SIRT5 in metabolic regulation, they have the potential to become a new direction in the treatment of metabolic diseases and tumors, and the development of related agonists or inhibitors will also become a hot field." (PMID 38773972, 2024). "Furthermore, considering that Sirt4 functions as a negative regulator of oxidative metabolism in humans and in D. simulans mtDNA haplotypes, D. simulans may be a more appropriate model organism compared to D. melanogaster for research on Sirt4 phenotypes and Sirt4-related metabolic disorders." (PMID 32152006, 2020).
cardiovascular disease (6 papers, 2015 to 2023). "Sirt4 also has an important role in insulin secretion, fatty acid oxidation, amino acid metabolism, ATP homeostasis, and cardiovascular diseases." (PMID 36160705, 2022). "Diet (CR) inhibits cardiovascular disease progression by increasing expression of SIRT4 and SIRT7." (PMID 33806509, 2021). "According to our results, acute short-term hypoxia might play an important additional role in the dysregulation of sirtuins, namely of SIRT1 and SIRT4, in cardiovascular disorders." (PMID 32796661, 2020). "SIRT4 overexpression in NRCMs decreased SIRT3-mediated MnSOD deacetylation and decreased its activity, promoting ROS accumulation during hypertrophic stress-inducing cardiovascular disorders." (PMID 34685718, 2021).
infection (6 papers, 2020 to 2025). The state of being infected such as from the introduction of a foreign agent such as serum, vaccine, antigenic substance or organism. "Interestingly, day 1 excluded, wMelCS infection was associated with the most consistent reduction in sirt-4 transcriptional levels (relative to uninfected group) across the timepoints tested, when compared to other strains." (PMID 33048997, 2020). "Quantitative real‐time polymerase chain reaction (qRT‐PCR) and western blot showed increased mRNA and protein levels of Sirt4 and Sirt5 in cardiomyocytes after Ad‐Sirt4 and Ad‐Sirt5 infection, respectively." (PMID 40842073, 2025). "Then, we constructed BLCA cell lines (T24) with overexpression or interference of SIRT4 by lentiviral infection." (PMID 37301821, 2023). "We overexpressed SIRT4 in PC-3 cells and knocked it down in 22rv1 cells, and its infection efficiency was determined by western blotting." (PMID 35847357, 2022). "Western blot results revealed that the expression of SIRT4, and a panel of stem cell-related molecules including ABCG2, BMI1, and NANOG was significantly suppressed in Hep-12 cells following infection with lentiviruses harboring SIRT4 shRNAs." (PMID 40384857, 2025).
neurodegenerative disease (6 papers, 2018 to 2026). A disorder of the central nervous system characterized by gradual and progressive loss of neural tissue and neurologic function. "SIRT4 expression and activity are mainly associated with susceptibility to endocrine diseases, tumors, and neurodegenerative diseases." (PMID 36760798, 2022). "The expression and activity of SIRT4 are related to the susceptibility of neurodegenerative diseases." (PMID 35652041, 2022). "Further studies linking neurodegenerative diseases and sirtuin members, especially SIRT4, 5, and 7, will be helpful to reveal the tissue or disease-specificity of the role of sirtuins." (PMID 30416425, 2018). "Activation of SIRT4 expression by RES may have a protective effect on neurodegenerative diseases, which was preliminarily validated in mice in our study." (PMID 35185463, 2022). "In addition to the role of SIRT3 in mitochondrial quality control in neurodegenerative diseases, recent studies have gradually started to investigate the roles of two other mitochondrial sirtuins, SIRT4 and SIRT5, in mitochondrial quality control." (PMID 31780922, 2019). "Although mitochondrial SIRT4 exhibits some therapeutic potential, SIRT4 remains the least studied SIRT, and its role in neurodegenerative diseases such as PD is largely unknown." (PMID 36760798, 2022).
Kidney Diseases (3 papers, 2021 to 2024). "SIRT4 is particularly crucial in kidney disease when it comes to mitochondrial function." (PMID 36139886, 2022). "Activity of SIRT4, another mitochondrial enzyme, in renal tissue and renal disease has not been strongly investigated yet." (PMID 39000044, 2024).
cardiac disease (2 papers, 2024 to 2025). "The present study provides novel mechanistic insights into the likely link between Sirt4 and heart regeneration, offering new therapeutic perspectives for ischaemic heart diseases." (PMID 40842073, 2025).
heart (1 paper, 2021). "SIRT4 also prevents hypoxia-induced apoptosis during ischemic heart injury." (PMID 33806509, 2021).
neurological disease (1 paper, 2023). "The modulating roles of SIRT4 in nervous system diseases have also been reported." (PMID 37647454, 2023). "Moreover, whether SIRT4 could be a predicting marker of neurological disease requires further analysis." (PMID 37647454, 2023).
psychiatric diseases (1 paper, 2024). "There are few published papers on the role of SIRT4 within psychiatric diseases, though there is a possibility that SIRT4 may play a role in the regulation of mood symptoms through its metabolic effects." (PMID 39404407, 2024).
SIRT4 also shares sentences with these, for which no sentence is quoted: liver cancer (5 papers); Glucose intolerance (3); adenocarcinoma (2); clear cell renal cell carcinoma (2); rectal cancer (2); bladder tumor (1); chronic obstructive pulmonary disease (1); CNS tumors (1); cognitive deficits (1); fibrosarcoma (1); head and neck squamous cell carcinoma (1); hepatic cirrhosis (1); infarction (1); injury (1); invasive breast carcinoma (1); leukemia (1); lipid metabolism disorders (1); lung adenocarcinoma (1); oral diseases (1); osteoporosis (1); peripheral artery disease (1); Premature ovarian insufficiency (1); proliferative diabetic retinopathy (1); retinopathy (1); Serous Ovarian Cancer (1); sexual dysfunction (1).